HULC (hepatocellular carcinoma up-regulated long non-coding RNA)
Synonyms: NCRNA00078; LINC00078; HCCAT1; LOC100506207
Gene: Long non-coding RNA gene on chromosome 6 (8,435,542 to 9,294,133, forward strand). Ensembl gene ENSG00000285219.
Gene Ontology:
Biological process: regulation of gene expression
Cellular component: ribosome
Diseases named in the same sentence as HULC in open-access papers:
HULC is named in the same sentence as 59 diseases in open-access papers, as found by Europe PMC text mining. Sharing a sentence is not in itself a finding about the gene and the disease. The quoted sentences say what the papers report.
hepatocellular carcinoma (100 papers, 2012 to 2026). A malignant tumor that arises from hepatocytes. "The rs7763881 SNP in the HULC locus was associated with decreased risk of hepatocellular carcinoma development in patients with persistent HBV infection." (PMID 33329688, 2020). "Pertinent to clinical practice, a genetic variant in the HULC gene has been found to alter the risk for hepatocellular carcinoma and oesophageal cancer, whereas cancer patients with high or low expression of HULC exhibit different clinical outcome." (PMID 27781386, 2017). "Subsequently, high levels of HULC were detected in the plasma of hepatocellular carcinoma patients and found to be associated with tumor aggressiveness and progression." (PMID 27253450, 2016). "Another study has reported that the interaction between HULC rs104127 and rs2038540 and the environment could increase the risk of hepatocellular carcinoma." (PMID 33119060, 2020). "HULC has been implicated in the regulation of hepatoma cell proliferation." (PMID 27782152, 2016). "HULC has emerged as a critical molecule in the progression of various digestive system malignancies, including hepatocellular carcinoma, pancreatic cancer, gastric cancer, and colorectal cancer liver metastasis." (PMID 40909946, 2025). "Increasing evidence suggests that HULC is aberrantly expressed in various gastrointestinal cancers, including hepatocellular carcinoma, gastric cancer, and colorectal cancer." (PMID 40909946, 2025). "Further studies revealed that HBx enhances hepatoma cell proliferation by upregulating the HULC/p18 pathway." (PMID 40909946, 2025). "Meanwhile, in vitro experiments have proved that CREB can up-regulate the expression of HULC, which inhibits p18 to promote the proliferation of hepatoma cells." (PMID 38334963, 2024). "Studies have pinpointed specific lncRNAs, such as HULC (Highly Upregulated in Liver Cancer) and HEIH (hepatocellular carcinoma UpRegulated EZH2-Associated Long Noncoding RNA), with elevated expression in HCC patients." (PMID 38203767, 2024). "HULC, a universal oncogenic lncRNA in human cancers, was reported to be strongly overexpressed in several cancer types, including hepatocellular carcinoma, gastric cancer, pancreatic cancer, and osteosarcoma." (PMID 36438902, 2022). "It has been reported that HULC can promote the phosphorylation of YB-1 protein to activate the translation of silent oncogenes, so as to promote the occurrence of hepatocellular carcinoma." (PMID 35183058, 2022). "In hepatocellular carcinoma, the binding of HULC to miR-372 attenuates miRNA-mediated translation inhibition of PRKACB and induces the phosphorylation of CREB." (PMID 34375306, 2021). "Our group has reported that MSL2 and HULC maintain HBV cccDNA minichromosome stability through the degradation of APOBEC3B in hepatoma cells." (PMID 34931766, 2021). "The lncRNA HULC is highly upregulated in hepatocellular carcinoma and has multiple binding sites with miR-372, which results in reduced translation of the target gene PRKACB." (PMID 34235197, 2021). "Diverse LncRNAs function as ceRNAs to adjust the EMT progression, such as LncRNA of HULC in hepatocellular carcinoma and LncRNA of H19 in colorectal cancer." (PMID 33311443, 2020). "Examples include lncRNA HULC, one of the most significant regulators in hepatocellular carcinoma whose overexpression inhibits miR-372 expression and further reduces translational repression of its target gene CREB in cell line Hep3B." (PMID 32846981, 2020). "Multiple miRNAs have been identified as targets of HULC in different diseases, such as miR-593 in hepatocellular carcinoma, miR-372 in liver cancer and so on." (PMID 32484206, 2020). "In a hepatoma mouse model, beneficial effects have been demonstrated by inhibition of the HULC/miR-9/PPARA/ACSL1/cholesterol/RXRA/HULC loop suggesting this feedback mechanism as a new potential therapeutic target." (PMID 31191327, 2019).
hepatocellular carcinoma (continued). "HULC has been reported as a highly upregulated gene in the hepatocellular carcinomas compared to healthy liver tissues (Xie, Ma & Zhou, 2013)." (PMID 29340250, 2018). "In this study, our results suggested that lncRNA HULC was highly up-regulation in human hepatocellular carcinoma." (PMID 29895332, 2018). "Up-regulated HULC by HBx promoted proliferation of hepatoma cells through regulating a tumor suppressor gene p18 located near HULC in the same chromosome." (PMID 29050269, 2017). "HULC (Highly Up-regulated in Liver Cancer) is the first characterized oncogenic lncRNA in hepatocellular carcinoma (HCC)." (PMID 28993733, 2017). "Elevated hepatic levels of HULC in hepatocellular carcinoma were mirrored in peripheral blood and plasma of affected individuals." (PMID 28829354, 2017). "Further research showed that HBx activates the HULC promoter via the CREB and that HULC upregulation enhances hepatoma cell proliferation by suppressing p18." (PMID 28835896, 2017). "For example, HULC is an lncRNA that is specifically overexpressed in hepatocellular carcinoma (HCC) and functions as a miRNA sponge to restrain the activity of many miRNAs, such as hsa-miR-372-5p, leading to the suppression of its target gene PRKACB." (PMID 28164117, 2017). "In recent years, HULC has been found to be dysregulated in osteosarcoma, pancreatic cancer, colorectal cancer, hepatocellular carcinoma, gastric cancer, hepatocellular carcinoma and large B-cell lymphoma." (PMID 28199963, 2017). "Further, HULC downregulated expression of p18, a tumor suppressor gene located in close proximity to HULC, leading to proliferation of hepatoma cells." (PMID 30159431, 2017). "In hepatoma cells, HBx was found to downregulate p18, which was reversed with HULC knockdown, implicating a mechanism in which HBx-mediated upregulation of HULC promotes the proliferation of hepatoma cells through downregulation of p18." (PMID 30159431, 2017). "As others long noncoding RNA (lncRNA), HULC has been shown to act as an oncogene in human hepatic carcinoma, esophageal cancer, osteosarcoma and pancreatic cancer." (PMID 26894862, 2016). "Our results demonstrate HULC, MALAT1 and TRF2 are highly expressed in human hepatocellular carcinoma tissues, and HULC plus MALAT1 overexpression drastically promotes the growth of liver cancer stem cells." (PMID 27782152, 2016). "Our group reported that the HBx-elevated HULC promoted hepatoma cell proliferation via decreased p18 and increased abnormal lipid metabolism in hepatoma cells through a miRNA-9 mediated RXRA signaling pathway." (PMID 26540633, 2016). "HULC activates the transcription of SPHK1 through transcriptional factor E2F1 in hepatoma cells, leading to up-regulation of SPHK1." (PMID 26540633, 2016). "HULC is the first ncRNA with highly specific up-regulation in hepatocellular carcinoma (HCC), but its functional contributions in this setting have not been determined." (PMID 27782152, 2016). "Mechanistically, HULC activated the promoter of SPHK1 in hepatoma cells through the transcription factor E2F1." (PMID 26540633, 2016). "Clinically, up-regulation of HULC has been detected in many human malignancies, such as esophageal cancer, osteosarcoma, pancreatic cancer and hepatocellular carcinoma." (PMID 26894862, 2016). "Other deregulations in proliferation pathways include the NFKB pathway, activated by BANCR in gastric cancer, and the lipid signaling molecules sphingosine kinases, activated by HULC in hepatocellular carcinoma." (PMID 27340923, 2016). "Recently, it was shown that HULC functions as an oncogene in hepatoma cells, acting mechanistically by promoting lipogenesis and disturbing the Clock circadian regulator (CLOCK)/brain and muscle arnt-like protein-1 (BMAL1) complex." (PMID 26887054, 2016).
hepatocellular carcinoma (continued). "HULC (highly up-regulated in liver cancer) has been identified as highly up-regulated in hepatocellular carcinoma and colorectal carcinomas that produce liver metastases but not in the primary colon tumors or their non-liver metastases." (PMID 25954300, 2015). "In other studies, HULC was shown to promote hepatoma cells proliferation by modulation of lipid metabolism." (PMID 26131450, 2015). "The proliferation, colony formation, and soft agar growth of liver cancer cells was reduced by inhibiting expression of the lncRNA TUC339 using an siRNA, while silencing HULC expression in hepatoma effectively inhibited the growth of liver cancer cells." (PMID 25200485, 2014). "ceRNAs can modulate self-regulation in hepatocellular carcinoma, e.g., HULC lncRNA acts as ceRNA of the protein coding gene PRKACB that induces activation of CREB which in turn is involved in upregulation of HULC." (PMID 25120561, 2014). "HBx-mediated up-regulation of HULC promotes the proliferation of hepatoma cells through the reduction of p18." (PMID 23762823, 2013). "HULC was identified as an lncRNA upregulated in human hepatocellular carcinoma (HCC) that is transcribed in a CREB-dependent manner." (PMID 23880895, 2013). "HBx from HBV upregulates HULC, a cellular lncRNA overexpressed in hepatocellular carcinoma." (PMID 41597397, 2026). "Collectively, these findings underscore the multifaceted role of HULC in hepatocellular carcinoma." (PMID 40909946, 2025). "HULC is an oncogenic lncRNA and may serve as a prognostic biomarker of hepatocellular carcinoma development." (PMID 38495672, 2024). "Similarly, the lncRNA HULC (highly upregulated in liver cancer) is overexpressed in hepatocellular carcinoma and promotes liver cancer growth through increasing the expression of the HMGA2 oncogene via sequestration of the microRNA-186." (PMID 37232821, 2023). "HULC is a lncRNA that is upregulated in hepatocellular carcinoma." (PMID 36824662, 2023). "Therefore, it can be concluded that the expression of HULC is involved in the proliferation of hepatoma cells and disease progression." (PMID 33736645, 2021). "HULC is highly upregulated in hepatocellular carcinoma and in several other cancers." (PMID 33425489, 2021). "HULC was first identified as an lncRNA overexpressed in hepatocellular carcinoma." (PMID 33329688, 2020). "HBx up-regulates HULC levels which in turn promotes hepatoma cell proliferation by suppressing p18." (PMID 30158867, 2018). "In oncology, Wang and colleagues found that the lncRNA MALAT1 is a biomarker for bladder carcinoma, Xie and his colleagues found that the lncRNA HULC is a biomarker for hepatocellular carcinoma, and Zhou and colleagues found that the lncRNA H19 is a possible diagnostic marker for gastric cancer." (PMID 29463949, 2017). "Corroboration between circulating and neoplasmic expression patterns thus provides a foundation upon which HULC might be developed as a noninvasive biomarker for the diagnosis and prognosis of hepatocellular carcinoma." (PMID 28829354, 2017). "Cui and colleagues found that HULC was an oncogene in hepatoma cells." (PMID 29137338, 2017). "High levels of the lncRNA HULC have been observed in hepatocellular carcinoma (HCC) tissues, as well as in metastatic tumours derived from the liver but not those from the lymph nodes, indicating that this lncRNA is specific to malignant cells located in the liver." (PMID 29137343, 2017). "In addition, we observed that the overexpression of HULC resulted in the down-regulation of miR-107 in hepatoma cells, suggesting that the interaction of HULC with miR-107 results in the decrease of miR-107." (PMID 26540633, 2016). "In addition, other potential plasma lncRNA markers have been identified, for instance, HULC for hepatocellular carcinoma, lncRNA-UCA1 for lung cancer, POU3F3 for esophageal squamous cell carcinoma." (PMID 27912775, 2016).
hepatocellular carcinoma (continued). "Given that HULC contributed to the proliferation and abnormal lipid metabolism of hepatoma cells, we speculated that HULC might contribute to the tumor angiogenesis." (PMID 26540633, 2016). "Indeed, HOTAIR, HULC and H19 expression levels in plasma have been demonstrated to correlate with outcome in series of patients with metastatic colon cancer, hepatocellular carcinoma and gastric cancer, respectively." (PMID 27340923, 2016). "We found that overexpression of HULC (or depletion of HULC) could enhance (or decrease) the secretion of S1P from hepatoma cells into the medium by SPHK1." (PMID 26540633, 2016). "Furthermore, plasma levels of HULC were increased in hepatocellular carcinoma, H19 in gastric cancer, and MALAT-1 in prostate cancer patients." (PMID 25685243, 2015). "In addition to liver cancer, HULC was found to be highly upregulated in hepatic colorectal cancer metastasis and in hepatocellular carcinoma cell lines (HCC) producing hepatitis B virus (HBV)." (PMID 22613733, 2012). "In HCC, the up-regulation of the lncRNA HULC (hepatocellular carcinoma up-regulated long noncoding RNA) was associated with the depletion of IGF2BP1, which recognizes m6A-modified HULC molecules and recruits the CCR4-NOT complex to initiate HULC degradation." (PMID 40584291, 2025). "Moreover, elevated intracellular cholesterol levels may further amplify HULC expression through activation of retinoid receptors in hepatoma cells, establishing a positive feedback loop that exacerbates tumor development." (PMID 40909946, 2025). "HULC could modulate gene expression through targeting miRNAs and mRNAs;19,21 however, it seems that these observations cannot account for the profound roles of HULC in hepatoma progression." (PMID 32572027, 2020). "We aimed to elucidate the diagnostic efficacy of eight serum lncRNAs HULC, MALAT1, Linc00152, PTENP1, PTTG3P, SPRY4-IT1, UBE2CP3, and UCA1 and their combinations for the diagnosis of hepatocellular carcinoma (HCC)." (PMID 32733618, 2020). "As indicated by a number of studies, lncRNA HULC is highly upregulated in liver cancer, functions as an oncogene in epithelial ovarian carcinoma, promotes proliferation and inhibits apoptosis in bladder cancer, and attenuates the chemosensitivity of hepatocellular carcinoma cells." (PMID 31319040, 2020). "Furthermore, HULC inhibits miR-9 mediated apoptosis in hepatocellular carcinoma cells." (PMID 31645479, 2019). "Especially in hepatocellular carcinoma (HCC), accumulating studies have been reported that lncRNA HULC has a potential as a promising therapeutic target in HCC and it can accelerate liver cancer by inhibiting PTEN via autophagy cooperation to miR15a." (PMID 31886187, 2019). "Thus, HULC promotes lipogenesis and malignancy in hepatoma cells." (PMID 28840253, 2018). "Some studies have reported that HULC is highly up-regulated in hepatocellular carcinoma (HCC) and colorectal cancer (CRC) that metastasized to livers." (PMID 29802154, 2018). "HULC (highly up-regulated in liver cancer) is overexpressed in liver cancer and can be detected in the plasma of hepatocellular carcinoma (HCC) patients." (PMID 27322075, 2016). "HULC might function through regulating a tumor suppressor gene p18 located near HULC in the same chromosome and the up-regulated HULC by HBx promotes proliferation of hepatoma cells through suppressing p1829." (PMID 27782152, 2016). "HULC is up-regulated in hepatocellular carcinoma (HCC), but it is over-expressed not only in HCC but also in CRC that has metastasized to the liver." (PMID 26637808, 2016). "Additionally, HBx could upregulate HULC expression in human immortalized normal liver L-O2 cells and hepatoma HepG2 cells and upregulation of HULC by HBx could promote proliferation of hepatoma cells through suppressing p18." (PMID 26136615, 2015).
hepatocellular carcinoma (continued). "Moreover, HBx could up-regulate HULC expression level in L-O2 cells (a human immortalized normal liver cell line) and HepG2 cells (a human hepatoma cell line)." (PMID 25387074, 2014). "Some of these lncRNAs include HOTAIR, HULC, PTV1, and MALAT1, which are also involved in the regulation of autophagy in hepatoma cells." (PMID 32473641, 2020). "HULC is the first lncRNA found to be specifically overexpressed in hepatocellular carcinoma (HCC)." (PMID 30134946, 2018). "HULC promotes tumor angiogenesis in liver cancer through miR-107/E2F1/SPHK1 signaling and modulates abnormal lipid metabolism in hepatoma cells through a miR-9-mediated RXRA signaling pathway." (PMID 28427159, 2017). "Recently, the mechanism and function of several lncRNAs such as HOTAIR, HULC, and MALAT1 were reported in hepatic carcinoma resulting in construction of lncRNA regulatory networks in hepatic carcinoma." (PMID 28938565, 2017). "In this study, we indicate that HULC, MALAT1 and TRF2 are highly expressed in hepatocellular carcinoma tissues, and present a positive correlation." (PMID 27782152, 2016). "HULC, MALAT-1, TUC338, TUC339, lncRNA-HEIH, MVIH, HOTAIR, lnc-RoR, and HOTTIP have all been associated with higher expression in hepatocellular carcinoma (HCC) compared with normal liver tissue, while MEG3 is repressed in HCC." (PMID 27007663, 2016). "To this data, we clearly identify that HULC, MALAT1 and TRF2 are highly expressed in hepatocellular carcinoma tissues, and present a positive correlation." (PMID 27782152, 2016). "The lncRNAs H19, HULC, HEIH, MVIH are highly upregulated in hepatocellular cancer and are valuable biomarkers for the same." (PMID 26082843, 2015). "Moreover, upregulation of HULC promotes the HBx/STAT3/miR-539/APOBEC3B pathway, which further supports HBV replication and accelerates hepatoma cell growth." (PMID 40909946, 2025). "Wang and his colleagues discovered that lncRNA HULC binds directly to LDHA and PKM2, affecting their cellular localization, phosphorylation level, and enzyme activity, thereby promoting aerobic glycolysis in hepatoma cells." (PMID 37328616, 2023). "In hepatocellular carcinoma (HCC), lncRNA HULC forms a positive feedback loop to promote adipogenesis and enhance tumor proliferation through the HULC/miR-9/PPARA/ACSL1/cholesterol/RXRA/HULC pathway." (PMID 36452489, 2022). "In 5 studies (1 on pancreatic cancer, 2 on hepatocellular carcinoma, and 2 on gastric cancer), the high expression of HULC was not significantly related to the age of patients (OR = 0.78, 95% CI: 0.55-1.10, P = 0.16)." (PMID 35183058, 2022). "Though the profile of miRNA was not evaluated in this study, HULC is known to modulate abnormal lipid metabolism in hepatoma cells through an miR9-medicated RXRA signaling pathway." (PMID 32413995, 2020). "For instance, HULC, up-regulated by CREB, could contribute to the initiation and progression of liver cancer through interacting with miR-372; lncRNA PVT1 favors hepatocellular carcinoma cell proliferation and stem cell-like property by stabilizing NOP2." (PMID 30987669, 2019). "Coregulation of genes by HULC and EZH2 or HULC and MLL1 was limited; however, there was significant negative correlation between HULC-regulated genes in SK-Hep-1 cells with genes regulated in hepatocellular carcinomas." (PMID 26317792, 2015). "Recently, several studies have demonstrated that two long non-coding RNAs (lncRNAs), HULC and MALAT1, may participate in hepatocellular carcinoma (HCC) development and progression." (PMID 22493738, 2012).